FOXS1 (forkhead box S1)
Description:
Transcriptional repressor that suppresses transcription from the FASLG, FOXO3 and FOXO4 promoters. May have a role in the organization of the testicular vasculature (By similarity).
Synonyms: FREAC-10; FKHL18; FREAC10
Tractability: No criterion of Open Targets' tractability assessment is met for any kind of drug.
Gene: Protein-coding gene on chromosome 20 (31,844,303 to 31,845,604, reverse strand). Ensembl gene ENSG00000179772.
Subcellular location: Nucleus
Subcellular location (Human Protein Atlas): Cytosol; Nucleoplasm
Gene Ontology:
Molecular function: DNA binding; DNA-binding transcription factor activity; DNA-binding transcription factor activity, RNA polymerase II-specific; RNA polymerase II cis-regulatory region sequence-specific DNA binding; DNA-binding transcription repressor activity, RNA polymerase II-specific; sequence-specific DNA binding
Biological process: anatomical structure morphogenesis; blood vessel development; cell differentiation; regulation of transcription by RNA polymerase II; negative regulation of transcription by RNA polymerase II; regulation of DNA-templated transcription
Cellular component: chromatin; nucleus
Genetic constraint (gnomAD): Loss-of-function variants: 8 observed, 15.06 expected, observed/expected ratio (o/e) 0.53, 90% interval 0.31 to 0.96. The upper end of that interval is the gene's LOEUF score, 0.96, which puts it in group 4 of 6, group 1 being the genes least tolerant of losing a copy. Missense variants: 414 observed, 480.97 expected, observed/expected ratio (o/e) 0.86, 90% interval 0.79 to 0.93. Synonymous variants: 161 observed, 197.99 expected, observed/expected ratio (o/e) 0.81, 90% interval 0.71 to 0.93.
Homologues: Orthologues: chimpanzee FOXS1 (99% identical), macaque FOXS1 (94% identical), dog FOXS1 (90% identical), pig FOXS1 (87% identical), rabbit FOXS1 (86% identical), guinea pig FOXS1 (86% identical), rat Foxs1 (77% identical), mouse Foxs1 (75% identical). Paralogues in human: FOXC1 (39% identical), FOXC2 (36% identical), FOXL1 (31% identical), FOXL2 (29% identical), FOXD2 (28% identical), FOXD1 (28% identical), FOXE3 (28% identical), FOXE1 (27% identical), FOXD3 (27% identical), FOXD4L1 (26% identical), FOXD4L3 (26% identical), FOXD4L5 (26% identical), and 29 more.
Diseases named in the same sentence as FOXS1 in open-access papers:
FOXS1 is named in the same sentence as 24 diseases in open-access papers, as found by Europe PMC text mining. Sharing a sentence is not in itself a finding about the gene and the disease. The quoted sentences say what the papers report.
gastric cancer (8 papers, 2016 to 2025). A primary or metastatic malignant neoplasm involving the stomach. "In summary, we first systematically identified FOXS1 as a novel oncogene and pinpointed the related regulatory network involved in FOXS1 in gastric cancer cells, providing new insight into understanding the mechanism underlying gastric cancer development." (PMID 30918291, 2019). "FOXS1, the most recent subfamily, is essential for the formation of the testicular vasculature and associated with the prognosis of human hepatocellular and gastric cancers." (PMID 35864528, 2022). "In univariate Cox proportion hazard ratio analysis, age, tumor(T) stage, Node(N) stage, metastasis(M) stage, FOXD3, FOXO4 and FOXS1 expression were significantly associated with prognosis in terms of OS of patients with gastric cancer in the TCGA cohorts (p < 0.05)." (PMID 27027443, 2016). "In the gastric cancer dataset, three genes—FOXS1, PGF, and CLDN1 —were commonly identified by both explainability methods and the manuscript, further validating their relevance." (PMID 40565055, 2025). "FOXS1, the most recent subfamily, is essential for forming the testicular vasculature and is related to human hepatocellular and gastric cancers." (PMID 35864528, 2022). "There are only a few studies that have reported that FOXS1 was involved in the regulation of cancer cell biology in gastric cancer, hepatocellular carcinoma, and glioma cells." (PMID 35898871, 2022). "In gastric cancer, FOXS1 overexpression inhibits EMT in SNU-216 cells but promotes EMT in SGC7901 and BGC823 cells." (PMID 35898871, 2022). "For examples, Lu reported that FOXS1 is downregulated in gastric cancer, and overexpression of FOXS1 inhibits proliferation, metastasis, and EMT in gastric cancer cell lines." (PMID 35898871, 2022). "The overexpression of FOXS1 in gastric cancer cell lines can inhibit proliferation, metastasis and epithelial-mesenchymal transition of tumor through downregulating wnt/β-catenin pathway." (PMID 31992202, 2020). "Although FOXS1 is predominately expressed in the nervous system, overexpression of FOXS1 can inhibit gastric cancer proliferation and metastasis." (PMID 32372224, 2020). "To validate the TCGA analysis results, we measured the expression of FOXS1 in 35 paired gastric cancer samples and paired precancer samples." (PMID 30918291, 2019). "Collectively, these results suggest that miR-125a-5p directly targets FOXS1 in gastric cancer cells, deregulating FOXS1 expression through translational repression." (PMID 30918291, 2019). "Despite the extensive efforts to understand the contribution of FOXS1 to gastric cancer, the mediators responsible for FOXS1 upregulation in gastric cancer remain unidentified." (PMID 30918291, 2019). "Using genome-wide methylation studies we identified lower FOXS1 methylation in gastric cancer, additional evidence indicating that FOXS1 is more highly expressed in gastric cancer tissues than in normal gastric tissues (P < 0.001)." (PMID 30918291, 2019). "The RT-PCR results showed that FOXS1 expression is significantly higher in gastric cancer tissues than in precancer tissues (P = 0.001)." (PMID 30918291, 2019). "To further prove the effect of FOXS1 on invasion and migration in gastric cancer, we performed WB analysis and immunofluorescence to measure the expression levels of EMT markers." (PMID 30918291, 2019). "To explore the clinicpathological role of FOXS1 in gastric cancer, we classified 376 patients into two groups on the basis of the mean FOXS1 expression level by analyzing TCGA data." (PMID 30918291, 2019). "In our work, the results of luciferase reporter assays showed that the core promoter regions of FOXS1 are located at nucleotides −660~ +1 in gastric cancer HGC-27 cells, but at −380 ~ +1 in SGC7901 cells." (PMID 30918291, 2019). "Currently, FOXS1 is known to be expressed only in the sensory nervous system, and the role and involved mechanism of FOXS1 in gastric cancers have been rarely reported." (PMID 30918291, 2019).
gastric cancer (continued). "These in vivo data further demonstrated that FOXS1 can promote gastric cancer tumorigenesis and EMT events." (PMID 30918291, 2019). "In this study, we concluded that FOXS1 was highly expressed in gastric cancer." (PMID 30918291, 2019). "To investigate the miRNA-related mechanism of FOXS1 upregulation in gastric cancer, we used 3 independent databases miRanda, mirDIP, and TargetScan to computationally predict miRNAs that may be involved." (PMID 30918291, 2019). "The findings of this study may potentially lead to the development of meaningful prognostic biomarkers for gastric cancer, and specific intervention strategies targeting FOXS1 might provide new therapeutic targets for gastric cancer patients." (PMID 30918291, 2019). "Unexpectedly, NFKB1 inhibited luciferase activity driven by F1100 in HGC-27 cells but slightly increased luciferase activity driven by F1100 in SGC7901 cells, suggesting that NFKB1 regulates FOXS1 expression in a manner dependent on the type of gastric cancer cells." (PMID 30918291, 2019). "The ROC analysis results revealed that FOXS1 could be a valuable biomarker for distinguishing gastric cancer patients from healthy persons, with an area under the curve (AUC) of 0.919." (PMID 30918291, 2019). "In addition, high FOXS1 expression indicated poor survival and differentiated gastric cancer from normal tissues with high sensitivity and specificity." (PMID 30918291, 2019). "In addition, FOXS1 expression was significantly higher in gastric cancer cells than in GES-1 cells (normal gastric epithelial cell) at both the transcriptional (P < 0.001) and translational levels." (PMID 30918291, 2019). "In our study, we found that FOXS1 was highly expressed in gastric cancer." (PMID 30918291, 2019). "Furthermore, to evaluate the usefulness of FOXS1 in discriminating gastric cancer patients from healthy persons, we performed receiver-operating characteristic (ROC) analysis." (PMID 30918291, 2019). "To assess whether FOXS1 could be used to predict gastric cancer development, we applied univariate and multivariate analyses." (PMID 30918291, 2019). "On the contrary, Wang’s study in a large sample size of clinical tissues showed that FOXS1 is upregulated in gastric cancer, and a high expression of FOXS1 significantly correlated with an aggressive phenotype and poor prognosis in patients with gastric cancer." (PMID 35898871, 2022). "In addition, miR-125a-5p could bind the 3′UTR of FOXS1 and regulate the expression of FOXS1 via translational repression in gastric cancer cells, which may lead to further advancements in the knowledge of gastric cancer tumorigenesis." (PMID 30918291, 2019). "Finally, miR-125a-5p bound the 3′UTR of FOXS1 and regulated the expression of FOXS1 via translational repression in gastric cancer cells, which may lead to further advancements in the knowledge of gastric cancer tumorigenesis." (PMID 30918291, 2019). "Overexpression of FOXS1 promoted cell proliferation and EMT in gastric cancer." (PMID 35898871, 2022). "We further investigated the effect of FOXS1 on the migration and invasive abilities of gastric cancer cells using in vitro Transwell assays with or without a Matrigel matrix layer on the inserts." (PMID 30918291, 2019). "To examine the expression of FOXS1 in gastric cancer, we found that FOXS1 was significantly highly expressed in gastric cancer, but not in six other kinds of cancers by using GEPIA online software." (PMID 30918291, 2019). "Taken together, regardless of previously contradictory reports in gastric cancer and hepatocellular carcinoma, our results indicate that FOXS1 might be a candidate oncogene in CRC." (PMID 35898871, 2022). "In our work, we found that FOXS1 expression was inversely correlated with the expression of epithelial markers (E-cadherin) and positively correlated with the expression of mesenchymal markers (vimentin and N-cadherin), indicating that FOXS1 could induce EMT in gastric cancer cells." (PMID 30918291, 2019).
gastric cancer (continued). "In this study, we found that FOXS1 expression was significantly correlated with GLI1 expression in the STAD tumor dataset but was not correlated with GLI1 expression in the STAD normal dataset, suggesting that GLI1 and FOXS1 may exhibit interplay in gastric cancer." (PMID 30918291, 2019).
glioma (4 papers, 2021 to 2024). A benign or malignant brain and spinal cord tumor that arises from glial cells (astrocytes, oligodendrocytes, ependymal cells). "The conditioned medium of glioma-associated MSCs has been shown to induce the overexpression of FOXS1 in glioma cells, which leads to the resistance of cancer cells to the chemotherapeutic agent temozolomide." (PMID 35954425, 2022). "Herein, we first demonstrate that the increased expression of FOXS1 is positively correlated with the effect of TMZ on glioma cells cultured in conditioned media (CM) of gaMSCs." (PMID 34256854, 2021). "Glioma cells with high FOXS1 expression formed larger tumours, expressed more Ki67 and were associated with shorter survival and EMT process activation, while glioma cells with low FOXS1 expression showed the opposite effects." (PMID 34256854, 2021). "We then show that FOXS1 expression in glioma cells was increased by secretion of IL-6 in conditioned media, which originated mainly from the CD90low gaMSC subpopulation." (PMID 34256854, 2021). "Here, we detected increased expression of FOXS1 in glioma cells, both the U87MG cell line and GBM-1 primary glioblastoma cell line, after indirect coculture with gaMSCs at the gene and protein levels." (PMID 34256854, 2021). "Then, FOXS1 expression in glioma cells was up- and downregulated by lentivirus transfection, and markers of the epithelial-mesenchymal transformation (EMT) process were detected." (PMID 34256854, 2021). "The results showed that the EMT process was activated in glioma cells with FOXS1 overexpression (OE-U87 and OE-GBM1) and suppressed in glioma cells with FOXS1 low expression (KD-U87 and KD-GBM1) when the cells were treated with TMZ." (PMID 34256854, 2021). "We subsequently compared the expression of FOXS1 in glioma cells that were cultured indirectly with the CD90high gaMSC and CD90low gaMSC subpopulations." (PMID 34256854, 2021). "After indirect culture with CD90low gaMSCs, glioma cells had higher expression of FOXS1 and EMT markers." (PMID 34256854, 2021). "The current findings suggest that CD90low glioma-associated mesenchymal stromal/stem cells promote chemotherapeutic resistance by activating FOXS1-mediated epithelial-mesenchymal transition in glioma cells." (PMID 34256854, 2021). "IL-6 increased the expression of FOXS1 in glioma cells compared to the control (DMEM medium) group, similar to gaMSCs." (PMID 34256854, 2021). "The results showed that the CD90low gaMSC subpopulation had a higher capacity to increase FOXS1 expression in glioma cells, both U87 and GBM-1." (PMID 34256854, 2021). "Finally, the expression of IL-6 in gaMSC subpopulations and its effects on FOXS1 expression in glioma cells were also investigated." (PMID 34256854, 2021). "In our study, we found that IL-6 in gaMSCs could increase the expression of FOXS1 in glioma cells, while the addition of an IL-6 neutralizing antibody could reverse this effect." (PMID 34256854, 2021). "Our data suggest that IL-6, mainly originating from CD90low gaMSCs, could increase the expression of FOXS1 in glioma cells and induce TMZ resistance." (PMID 34256854, 2021). "Overall, we found that gaMSCs could increase the TMZ resistance of glioma cells via overexpression of FOXS1." (PMID 34256854, 2021). "The expression of FOXS1 in glioma cells was analysed by gene microarray, PCR and Western blotting." (PMID 34256854, 2021). "On the other hand, low expression of FOXS1 in glioma cells induced increased sensitivity to TMZ." (PMID 34256854, 2021). "Moreover, FOXS1 expression in glioma cells was increased by secretion of IL-6 mainly from the CD90low gaMSC subpopulation." (PMID 34256854, 2021). "Furthermore, we confirmed the variation in FOXS1 expression at the mRNA and protein levels in glioma cells (both in the U87MG cell line and in GBM-1 primary glioblastoma cells) when glioma cells were cultured in conditioned media of gaMSCs for 3 days." (PMID 34256854, 2021).
glioma (continued). "Furthermore, we proved that FOXS1 upregulation was related to TMZ resistance in glioma cells." (PMID 34256854, 2021). "Recently, it has been reported that FOXS1 promoted EMT and was related to temozolomide resistance in glioma cells." (PMID 35898871, 2022). "The increased expression of FOXS1 and activation of the EMT process in glioma cells under gaMSC-conditioned media were detected." (PMID 34256854, 2021). "The CD90low gaMSC subpopulation, which is a newly identified recruited component in the tumour microenvironment, secreted IL-6, which then upregulated FOXS1 expression and activated the EMT process, thus contributing to TMZ resistance in glioma cells." (PMID 34256854, 2021). "The markers of the EMT process were changed in response, and the results suggested that FOXS1 activated the EMT process, thus contributing to TMZ resistance in glioma cells." (PMID 34256854, 2021). "The relationship of FOXS1, EMT and chemotherapy resistance in glioma cells was demonstrated through the regulation of FOXS1 expression in vitro and in vivo." (PMID 34256854, 2021). "CD90low gaMSCs could increase FOXS1 expression in glioma cells by IL-6 secretion, thereby activating epithelial-mesenchymal transition and resistance to TMZ in glioma cells." (PMID 34256854, 2021). "gaMSCs can increase FOXS1 expression and thus activate the EMT process in gliomas." (PMID 34256854, 2021).
breast carcinoma (3 papers, 2018 to 2025). "In this direction is also the protective role of FOXS1 expression in relapse‐free survival of breast cancer, another tumor where GLI1 signaling has been implicated." (PMID 30098229, 2018). "Consistently, high FOXS1 expression predicts longer relapse‐free survival in breast cancer." (PMID 30098229, 2018).
colorectal cancer (3 papers, 2022 to 2023). A primary or metastatic malignant neoplasm that affects the colon or rectum. "The value of FOXD4, FOXH1, and FOXS1 were significantly up-regulated in colorectal cancer relative to the control (FC > 1.5 and P < 0.05)." (PMID 38310407, 2023). "However, the role and mechanism of the FOXS1 in colorectal cancer (CRC) remain unclear." (PMID 35864528, 2022).
medulloblastoma (3 papers, 2018 to 2021). A malignant, invasive embryonal neoplasm arising from the cerebellum. "The finding of a FOXS1/GLI1 feedback loop may also provide additional possibilities to develop effective markers for SHH medulloblastoma." (PMID 30098229, 2018). "An interesting question in this context is whether the FOXS1 co‐expression to the GLI1 oncogene in medulloblastoma and prostate cancer promotes or inhibits tumorigenesis." (PMID 30098229, 2018). "Importantly, we now demonstrate a prominent FOXS1 expression in Sonic HH medulloblastomas." (PMID 30098229, 2018). "Finally, FOXS1 expression highly correlated with GLI1 expression in SHH medulloblastoma." (PMID 30098229, 2018). "Furthermore, one of the top targets, FOXS1, a gene encoding a transcription factor previously implicated in nervous system development, was shown to act in a negative feedback loop limiting the cellular effects of GLI1 in medulloblastoma and rhabdomyosarcoma cells." (PMID 30098229, 2018). "Moreover, FOXS1 is both highly expressed and positively correlated with GLI1 in medulloblastoma samples of the Sonic HH subgroup, further arguing for the existence of FOXS1/GLI1 interplay in human tumors." (PMID 30098229, 2018).
hepatocellular carcinoma (2 papers, 2022). A malignant tumor that arises from hepatocytes. "Moreover, FOXS1 induced by TGFβ promoted a classical model of EMT by activating the expression of EMT-transcription factors (SNAI1, and SNAI2) in hepatocellular carcinoma." (PMID 35898871, 2022).
liver cancer (2 papers, 2019 to 2022). An epithelial or non-epithelial malignant neoplasm that arises from the liver. "Nevertheless, FOXS1 has the opposite characteristic in liver cancer; it is expressed at lower levels in most HCC tissues than in normal liver tissues." (PMID 30918291, 2019). "A high expression of FOXS1 predicted a poor prognosis in liver cancer." (PMID 35898871, 2022). "In addition, overexpression of FOXS1 induced EMT markers and promoted cell migration and metastasis in liver cancer." (PMID 35898871, 2022).
liver fibrosis (2 papers, 2025). "Hepatic stellate cell myofibroblast activation significantly contributes to liver fibrosis, further highlighting that FOXS1 may be crucial for aberrant myofibroblast activation in tissue-resident stem cells that drives tissue fibrosis." (PMID 40774386, 2025). "The transcription factor Forkhead Box 1 (FOXS1) is an emerging biomarker in liver fibrosis, and it could be that it is essential for insulin resistance to initiate fibrotic pathways, as CRISPR FOXS1 knockout in human LX2 HSCs increased the kinase activity of the insulin receptor." (PMID 40985048, 2025).
adrenocortical tumors (1 paper, 2018). "It has also been reported that Foxs1 is hypomethylated and up‐regulated in murine postgonadectomy adrenocortical tumors." (PMID 30098229, 2018).